CRPPA (CDP-L-ribitol pyrophosphorylase A)
Description:
Cytidylyltransferase required for protein O-linked mannosylation. Catalyzes the formation of CDP-ribitol nucleotide sugar from D-ribitol 5-phosphate. CDP-ribitol is a substrate of FKTN during the biosynthesis of the phosphorylated O-mannosyl trisaccharide (N-acetylgalactosamine-beta-3-N-acetylglucosamine-beta-4-(phosphate-6-)mannose), a carbohydrate structure present in alpha-dystroglycan (DAG1), which is required for binding laminin G-like domain-containing extracellular proteins with high affinity. Shows activity toward other pentose phosphate sugars and mediates formation of CDP-ribulose or CDP-ribose using CTP and ribulose-5-phosphate or ribose-5-phosphate, respectively. Not Involved in dolichol production.
Synonyms: hISPD; ISPD; hCG_1745121; Nip; LGMDR20; MDDGA7; MDDGC7
Tractability: No criterion of Open Targets' tractability assessment is met for any kind of drug.
Gene: Protein-coding gene on chromosome 7 (16,087,525 to 16,502,504, reverse strand). Ensembl gene ENSG00000214960.
Subcellular location: Cytoplasm, cytosol
Subcellular location (Human Protein Atlas): Nucleoli fibrillar center; Nucleoplasm
Pathways (Reactome):
Metabolism of proteins: Matriglycan biosynthesis on DAG1
Gene Ontology:
Molecular function: cytidylyltransferase activity; D-ribitol-5-phosphate cytidylyltransferase activity; protein homodimerization activity; catalytic activity
Biological process: protein O-linked glycosylation via mannose; glycoprotein biosynthetic process; isoprenoid biosynthetic process
Cellular component: cytosol
Genetic constraint (gnomAD): Loss-of-function variants: 16 observed, 16.6 expected, observed/expected ratio (o/e) 0.96, 90% interval 0.65 to 1.46. The synonymous counts are far from expectation, so gnomAD's model fits this gene poorly and the ratio says little. Missense variants: 350 observed, 275.81 expected, observed/expected ratio (o/e) 1.27, 90% interval 1.16 to 1.39. Synonymous variants: 144 observed, 105.23 expected, observed/expected ratio (o/e) 1.37, 90% interval 1.19 to 1.57.
Gene-disease validity (ClinGen):
ClinGen rates the evidence that CRPPA causes each of these diseases.
myopathy caused by variation in CRPPA (autosomal recessive): Definitive. Any myopathy in which the cause of the disease is a variation in the CRPPA gene.
Homologues: Orthologues: chimpanzee CRPPA (99% identical), macaque CRPPA (94% identical), pig CRPPA (81% identical), rabbit CRPPA (78% identical), mouse Crppa (74% identical), rat Crppa (73% identical), guinea pig CRPPA (67% identical), dog CRPPA (64% identical), tropical clawed frog crppa (53% identical), zebrafish crppa (45% identical).
Diseases named in the same sentence as CRPPA in open-access papers:
CRPPA is named in the same sentence as 23 diseases in open-access papers, as found by Europe PMC text mining. Sharing a sentence is not in itself a finding about the gene and the disease. The quoted sentences say what the papers report.
dystroglycanopathies (12 papers, 2013 to 2025). "According to OMIM, pathogenic variants in CRPPA are associated with muscular congenital dystrophy‐dystroglycanopathy with brain and eye anomalies and limb‐girdle muscular dystrophy‐dystroglycanopathy." (PMID 40525497, 2025). "In addition to generating dystroglycanopathies, CRPPA mutations have also been linked to limb girdle muscular dystrophy, Walker–Warburg syndrome, and muscle–eye–brain disease." (PMID 36358336, 2022).
muscular dystrophy-dystroglycanopathy (2 papers, 2024). "Muscular dystrophy-dystroglycanopathy (congenital with brain and eye anomalies), type A, 7 (OMIM: 614643), and muscular dystrophy-dystroglycanopathy (limb-girdle), type C, 7 (OMIM: 616052) are diseases linked to the CRPPA gene." (PMID 40225931, 2024).
leukemia (1 paper, 2022). A malignant (clonal) hematologic disorder, involving hematopoietic stem cells and characterized by the presence of primitive or atypical myeloid or lymphoid cells in the bone marrow and the blood. "Furthemore, in solid tumors and derived cell lines (i.e., leaving aside leukemia) genes directly involved in the synthesis of core M3 glycan and matriglycan, such as POMGNT2, CRPPA, B4GAT1, LARGE1 and LARGE2 and/or their encoded proteins, are found downregulated." (PMID 36494657, 2022).
CRPPA also shares sentences with these, for which no sentence is quoted: limb-girdle muscular dystrophy (5 papers); Walker-Warburg syndrome (5); congenital muscular dystrophy (3); tuberculosis (3); tumor (3); cancer (2); infection (2); malaria (2); brain disease (1); clear cell renal cell carcinoma (1); Cognitive impairment (1); dysferlinopathy (1); influenza (1); Mental Retardation (1); muscular atrophy (1); muscular dystrophy (1); neurological disorder (1); renal cell carcinoma (1); respiratory failure (1); urethritis (1).